CD4 (CD4 molecule)
Diseases named in the same sentence as CD4 in open-access papers (continued):
Sharing a sentence is not in itself a finding about the gene and the disease.
schistosomiasis (continued). "The CD4+ T cell subsets are involved in the regulation of schistosomiasis progression." (PMID 27792733, 2016). "The CD4+ T cell subsets play a critical role to develop hepatic granulomas and to maintain a balanced granulomatous response to prevent the growth of hepatic fibrosis during schistosomiasis." (PMID 27792733, 2016). "In summary, by using AQP4 KO mouse model of schistosomiasis japonica, we demonstrated for the first time an association of AQP4 with the immunoregulation of the liver pathology suggested an important role for AQP4 in regulation of CD4+ T cells differentiation in schistosomiasis." (PMID 25604731, 2015). "Thus, we expect that the cooperation between CD8+T cells, CD4+T cells and IgG responses would achieve an effective protection against schistosomiasis." (PMID 26714844, 2015). "The frequency of CD4+ T cells among total lymphocytes was comparable between patients and healthy controls, although the percentage of T cells was slightly lower in patients with schistosomiasis." (PMID 26284362, 2015). "Furthermore, we found that the percentage of circulating Tfr cells within CD4+ T cells or total Tfh cells was significantly increased in schistosomiasis patients." (PMID 26284362, 2015). "Interestingly, whereas all eGFP+ CD4 T cells during schistosomiasis preserved CD200R, only a proportion secreted IL-4 indicating that not all Th2-primed cells acquired/retained effector function." (PMID 22496920, 2012). "Importantly, our data indicate that CD200R expression by CD4 T cells is a useful indicator of infection intensity and T cell function in areas of endemic schistosomiasis." (PMID 22496920, 2012). "A substantial body of evidence indicates that CD4+ T cell subsets, including Th1, Th2, Th17, Tfh (T follicular helper, Tfh), Th9, and Treg (regulatory T, Treg) cells, are critically involved in the pathogenesis of liver granuloma formation and fibrosis during schistosomiasis." (PMID 41154658, 2025). "However, how could the CD4+ T-cell response to a single epitope determine the outcome of a complex disease such as schistosomiasis?" (PMID 39661861, 2024). "Consistent with the previously reported higher expression rate of Batf2 by CD8+ T cells when compared to CD4+ T cells, our present data reveal a more pronounced inflammatory surge in CD8+ cells within the T cells compartment of Batf2-deficient mice during acute schistosomiasis." (PMID 30542107, 2019). "It is currently unknown if PD-1 is induced in CD4+ T cells in schistosomiasis patients." (PMID 27792733, 2016). "However, whether Tfh cells, as the other CD4+ T cell populations (Th1, Th2, Th17 and Treg cells) do, contribute to the liver pathology in mice with schistosomiasis remains to be explored." (PMID 24788758, 2014). "It has been suggested that PZQ has strong regulatory effects on cell immunological responses, reducing CD4+T cells while increasing CD8+ cells, resulting in a smaller hepatic granuloma size in schistosomiasis." (PMID 37339146, 2023). "Schistosomiasis treatment induces a profound reduction of HIV entry into cervical and blood CD4+ T cells that is sustained for up to two months, despite transient systemic and mucosal immune activation and elevated genital IL-1α levels." (PMID 31127086, 2019). "In Schistosoma infection, natural Treg cells (CD4+CD25+) and, to a lesser extent, Th2 cells play roles in the suppression of Th1 responses during schistosomiasis." (PMID 30687325, 2018). "Treatment of schistosomiasis leads to a decrease in the level of CCR5 and CXCR4 on CD4+ cells in both HIV infected and uninfected patients." (PMID 24472559, 2014). "Althoughprevious studies point to the importance of CD4+CD25+Tregs in the host response to cancer and other diseases, the influence ofthese cells on the response to a schistosomiasis vaccine has yet to be examined." (PMID 22802961, 2012).
schistosomiasis (continued). "In schistosomiasis-induced fibrosis models, ARG1 deletion led to an increase in type 2 inflammation and consequently increased fibrosis because of an accumulation of arginine, which supports CD4+ T cell proliferation." (PMID 40875483, 2025). "In addition to the various subsets of CD4+ T-cells, CD8+ T-cells are also involved in the liver injury and fibrosis of schistosomiasis." (PMID 39590301, 2024). "CD4+ T cells are the key factors involved in the development of immunopathology in schistosomiasis; however, pioglitazone treatment did not influence the numbers of CD4+ T cells in S. japonicum-infected mice." (PMID 30116754, 2018). "Our findings indicate that the mean CD4 cell count in women was not influenced by schistosomiasis or that the level of egg excretion was influenced by CD4 cell count." (PMID 25768005, 2015). "Studies have shown that CD4+CD25+Foxp3+ Treg cells are induced mainly by egg antigens during the infection, and play an important suppressive role in down-modulating granulomatous response in schistosomiasis." (PMID 25604731, 2015). "However, treatment of schistosomiasis leads to a decrease in the level of CCR5 and CXCR4 on CD4+ cells in both HIV infected and uninfected patients." (PMID 24472559, 2014). "B cells, however, are reported to down-regulate granulomatous pathology in schistosomiasis, but not to affect the development of blood flukes together with CD4+ T lymphocytes." (PMID 23349889, 2013). "In addition to the various subsets of CD4+ T-cells, CD8+ T-cells may also be involved in the liver injury and fibrosis of schistosomiasis." (PMID 39590301, 2024). "A systemic effect of schistosomiasis was also described in individuals infected with S. mansoni who expressed a higher, but not statistically significant, density of the CCR5 receptor on CD4+ T-cells and monocytes in blood which then decreased after anti-schistosomal treatment." (PMID 24896815, 2014). "Given the potential role of CD4+CD25+ Tregcells in suppressing the immune response induced by vaccination, a key questionis whether the depletion of this cell type affects the protective efficacyof the pVAX1-Sj26GST schistosomiasis vaccine." (PMID 22802961, 2012). "We next compared the density distribution of CD4 + and CD8 + T cells in CRC patients with and without schistosomiasis (data was not shown)." (PMID 37277702, 2023). "Praziquantel administration, in the absence of schistosomiasis, did not tend to reduce HIV entry into blood-derived CD4+ T cells or alter systemic CD69+ CD4+ T cell frequency." (PMID 31127086, 2019). "In infected PD-1-deficient mice, we observed a significant increase in IFN-γ production in CD4+ and CD8+ T cells, and higher T-bet expression in CD4+ T cells but not in CD8+ T cells, suggesting the existence of IFN-γ driving transcriptional program independent of T-bet during schistosomiasis." (PMID 35666747, 2022). "For schistosomiasis, but not ascariasis, six months after anti-helminthic treatment, the CD4+ T cell immune phenotype demonstrated an increase percentage of IL-4 producing and decreased percentage of TNF and IFN-γ producing antigen-specific CD4+ T cells compared to uninfected controls." (PMID 33668787, 2021). "Recently, studies have shown that AQP4 expresses in immune system and lack of AQP4 in mice results in significantly less CD4+CD25+ T regulatory cells (Treg cells) under physiological condition, one of the subpopulations of CD4+T cells which restrains immunopathology in hosts with schistosomiasis." (PMID 25604731, 2015).
ulcerative colitis (95 papers, 2012 to 2026). An inflammatory bowel disease involving the mucosal surface of the large intestine and rectum. "Moreover, we have demonstrated that probiotic administration in patients with ileal pouch anal anastomosis for ulcerative colitis is associated with an increased percentage of CD3+CD4+LAP+ cells in the pouch LP and a decrease in pouch disease activity index." (PMID 30425718, 2018). "We further showed that patients with ulcerative colitis exhibited significant gut dysbiosis and CD4+ T cell differentiation abnormalities." (PMID 40469515, 2025). "PER2 downregulated a disintegrin and metalloproteinase 12 (ADAM12) expression by reducing its binding activity, thereby suppressing IFN‐γ production in CD4 + T cells of ulcerative colitis." (PMID 40911428, 2025). "In this study, we discovered that Nat10 expression correlates with inflammatory and apoptotic pathways in human ulcerative colitis CD4+ T cells." (PMID 40038243, 2025). "Ulcerative colitis (UC) is characterized by complex immunological interactions involving CD4 T cell subsets and the NLRP3 inflammasome, which influence inflammatory responses." (PMID 39833691, 2025). "In ulcerative colitis, a Th2-type immune response predominates, leading to an increase in CD4+ T cells and the release of cytokines that promote inflammation." (PMID 39449918, 2024). "CD4 CTL and CD8 Te1, known for their cytotoxic roles in autoimmune conditions like ulcerative colitis, were implicated in local lesion exacerbation by upregulating inflammatory mediators." (PMID 39365735, 2024). "Low LRCH1 levels, which increase migration of CD4+ T cells, have also been found in patients with ulcerative colitis." (PMID 37365285, 2023). "Greater CD8+ lymphocyte involvement and higher CD8+/CD4+ distribution can have a meaningful impact on understanding the pathogenesis and natural history of ulcerative colitis, as well as future treatment options for lymphocyte-targeting medications." (PMID 37509500, 2023). "CD4+ lymphocytes are the main inflammatory cells involved in ulcerative colitis’ pathology, while CD8+ cells can have pro-inflammatory and immunosuppressant effects." (PMID 37509500, 2023). "Unsupervised/supervised methods identified significant differences in the expression profiles of CD4 T-cells between patients with ileal Crohn’s disease (CD) and ulcerative colitis (UC)." (PMID 36746519, 2023). "The amount of CD4+CD161+ T cells was observed significantly decreased in active ulcerative colitis (UC) compared with inactive UC." (PMID 37063924, 2023). "In biopsies obtained from inflamed tissue of ulcerative colitis (UC) patients, we found that CD4 T cells in general increase in numbers." (PMID 36463279, 2022). "The Th1/Th2 balance of peripheral CD4-positive T cells is considered a biomarker for patients with refractory ulcerative colitis." (PMID 34456974, 2021). "In a study of ulcerative colitis, CD4+CD25+ Tregs in rat peripheral blood were negatively correlated with IL-10 levels." (PMID 32218692, 2020). "We have previously shown that the T helper- (Th-) type 2 cytokines, Interleukin- (IL-) 4 and IL-13, mediate CD4+ T cell- or B cell-driven inflammation in the oxazolone-induced mouse model of ulcerative colitis." (PMID 32410852, 2020). "Authentically, ulcerative colitis can be alleviated by regulating the differentiation of naïve CD4+ T cells via AhR activation." (PMID 33082710, 2020). "IL18R1 has previously been found to have colocalized disease and eQTL association patterns in CD4 and CD8 cells for both ulcerative colitis and Crohn’s disease." (PMID 31727947, 2019). "We evaluated the in-vitro effect of potassium on CD4+ T cells and the role of urinary potassium as a potential biomarker of disease activity in patients with ulcerative colitis (UC)." (PMID 29273710, 2017).
ulcerative colitis (continued). "In contrast, specimens from patients with ulcerative colitis refractory to medical therapy contained significantly more CCR9 expressing CD4+ (92.6 ± 4.1%; p < 0.001) and CD8+ T-cells (34.3 ± 3.8%; p = 0.013) than non-inflamed colon." (PMID 26873648, 2016). "Decreased plasma levels of hs-CRP, TNF-α, plasma DA0, ET, D-lactic acid, IL-8, and IL-6 and increased CD4/CD8 ratio and CD4+ levels, enhancing the remedying impact in ulcerative colitis patients and regulating T cell frequency, in addition to reducing plasma inflammatory factors." (PMID 38398870, 2024). "Here, CD4+ T cells mediate the pathogenesis of ulcerative colitis and massively infiltrate into the colonic mucosa, potentially by a mechanism negatively regulated by LRCH1 as migration of CD4+ T cells from ulcerative colitis patients is reduced by LRCH1 overexpression." (PMID 33072765, 2020). "Similarly, migration of CD4+ T cells from ulcerative colitis patients is increased compared to CD4+ T cells from healthy individuals." (PMID 33072765, 2020). "Therefore, it can regulate intestinal stem cells, CD4+ T cells, innate lymphoid cells, macrophages, and intestinal microbiota and intervene in the chemical, physical, immune, and biological mucosal barriers in cases of ulcerative colitis." (PMID 38249980, 2023). "During the active phase of ulcerative colitis, CD8+ cells were present in higher numbers compared to intraepithelial CD4+ cells (mean 11.25 vs. 6.8 cells/100 epithelial cells), reflecting their prominent role in mucosal immunity." (PMID 41465205, 2025). "The aim of this work was to assess whether baseline circulating CD4+ and CD8+ memory T-lymphocyte subpopulations could help to identify patients with response to vedolizumab treatment in ulcerative colitis." (PMID 35783609, 2022). "Acute ulcerative colitis induced by DSS showed intestinal bacterial infection and was characterized by massive infiltration of proinflammatory cells, such as macrophages, neutrophils, and CD4+ T cells, within the colonic walls, which destroy epithelium and shorten the colon length." (PMID 27313642, 2016). "In the mdr1a−/− mouse model of ulcerative colitis, increased colonic CCL25 protein levels were noted before any clinical manifestations of disease and correlated temporally with increases in the frequency of circulating CCR9+CD4+ T cells, which we used as a surrogate for intestinal inflammation." (PMID 26457007, 2015). "Third, only a limited set of immune markers (CD4, CD8, and IL-6) was analyzed; inclusion of additional cytokines and functional markers (e.g.,TNF-α, TGF-β, FOXP3, IL-17, granzyme B) could provide a more comprehensive understanding of immune regulation in ulcerative colitis." (PMID 41465205, 2025). "Therefore, despite the lack of a difference in the CD4+/CD3+ fraction, the decrease in the CD8+/CD3+ ratio in pouchitis patients with ulcerative colitis is consistent with previous reports." (PMID 39449918, 2024).
toxoplasmosis (91 papers, 2010 to 2026). A parasitic disease contracted by the ingestion or fetal transmission of toxoplasma gondii. "On the other hand, the number of CD4 + count (<200/mm3) is a significant risk factor for toxoplasmosis in PLWH." (PMID 36840494, 2023). "We expect that one of the most important risk factors for toxoplasmosis in HIV+ is a low CD4+ lymphocyte count." (PMID 34683355, 2021). "Associated with increased pro-inflammatory cytokines during toxoplasmosis, IL-10 plays a central role in reducing inflammation and severe immunopathology mediated by CD4+ T cells." (PMID 34683874, 2021). "The significance of adaptive immunity in human toxoplasmosis is established in patients with acquired or primary defects in T cells; also, mice with deficient B cells, CD4+ T cells or CD8+ T cells showed increased susceptibility to T. gondii infection." (PMID 33575600, 2020). "Collectively, these results indicated that Ahr-/- mice developed a hyperactivated CD4+ T cell response during toxoplasmosis and were more susceptible to this challenge." (PMID 26010337, 2015). "Both CD8+ and CD4+ T cells play an important role in resistance to T. gondii in mice; this was also indicated by the susceptibility of individuals with T cell deficiencies to toxoplasmosis." (PMID 30040611, 2018). "A low CD4+/CD8+ ratio (≤ 0.3–0.4) indicates a higher risk of reactivation and complications for HIV patients with toxoplasmosis." (PMID 40709328, 2025). "We conducted a study on T-cell function by measuring the cytokine production of IFN-gamma in patients with HIV and toxoplasmosis, particularly those showing signs of immune suppression (CD4/CD8 < 0.4)." (PMID 40709328, 2025). "That makes it a valuable tool for investigating CD4 T cell responses in patients with toxoplasmosis." (PMID 40709328, 2025). "Seven HIV-infected patients who tested positive for toxoplasmosis showed low CD4+/CD8+ T cell ratios during immunological monitoring." (PMID 40709328, 2025). "The CD4+T cell count was relatively lower in toxoplasmosis-infected patients (430–450 cells/mm3) than in control group (500–1500 cells/mm3)." (PMID 38172676, 2024). "▪Primary prophylaxis in Toxoplasma IgG-positive patients until CD4+ count is >200 cells/μL in response to ART.▪All regimens recommended for primary prophylaxis against toxoplasmosis are also effective as PJP prophylaxis." (PMID 39459894, 2024). "Toxoplasmosis was less likely with increasing CD4 counts (51–100 cells/μL: OR 0.41, 95% CI 0.18–0.96; 101–200 cells/μL: OR 0.14, 95% CI 0.06–0.34; >200 cells/μL: OR 0.02, 95% CI 0.01–0.06), when compared to CD4 ≤50 cells/μL." (PMID 38950027, 2024). "Toxoplasmosis was less likely with in patients with higher CD4 counts (51–100 cells/μL: OR 0.41, 95% CI 0.18–0.96; 101–200 cells/μL: OR 0.14, 95% CI 0.06–0.34; >200 cells/μL: OR 0.02, 95% CI 0.01–0.06) compared to in patients with CD4 ≤50 cells/μL." (PMID 38950027, 2024). "Initial lab tests showed toxoplasmosis IgG reactive serology for human immunodeficiency virus 1 (HIV-1) was positive with a CD4 cell count of 43 cells/mm3." (PMID 39473656, 2024). "In recent years, due to a lack of an effective vaccine, effective prophylactic strategies for toxoplasmosis, especially in pregnant women and/or immunocompromised patients with a CD4 < 100 cells/μl, have been strongly recommended." (PMID 37249978, 2023). "After receiving transfer of CD8+ or CD4+ splenocytes from Hsp70-immunized mice, the T. gondii load was limited in the acute and chronic phases of toxoplasmosis." (PMID 37122740, 2023). "As such, the clinical courses of OIs (e.g., toxoplasmosis and Cytomegalovirus infections) were correlated with a decline in the CD4 + cell count." (PMID 36840494, 2023). "The transient decrease in CD4 counts observed early in the course of certain cases of severe toxoplasmosis likely contributed to the observed severity." (PMID 37111429, 2023).